IDO1 (indoleamine 2,3-dioxygenase 1)
Diseases named in the same sentence as IDO1 in open-access papers (continued):
Sharing a sentence is not in itself a finding about the gene and the disease.
tumor (continued). "Indeed, IDO1 was induced in tumours treated with either viruses or CD8+NKG2D+ cells alone, and was intensively induced in tumours treated with both." (PMID 28701757, 2017). "In tumours, IDO1 can be induced by antitumour immunotherapy." (PMID 28701757, 2017). "As expected, IDO1 expression was undetectable in xenografts when tumor cells were inoculated alone." (PMID 26895379, 2016). "Tumor endothelial cells appear to express IDO1 in human RCC as has been previously suggested." (PMID 27572319, 2016). "In that regard, genetic studies in mice demonstrated that Bin1 mutations could potentiate IFN-γ-induced NFκB and STAT-dependant IDO1 overexpression in tumor cells." (PMID 26895379, 2016). "IDO1-expression is associated with increased differentiation of naïve CD4 T cells into Tregs in humans, and with increased infiltration of Tregs in tumor." (PMID 27192116, 2016). "We then investigated whether human tumor cell lines oriented from hepatocelluar carcinomas constitutively expressed IDO1 in vitro." (PMID 26895379, 2016). "Indeed, IDO1 down-regulation can impair both mTOR activation and Treg-dependent tumor immune escape mechanism." (PMID 27174915, 2016). "This again raises the possibility that IDO1 locality determines whether it supports or prevents tumour growth." (PMID 26646699, 2016). "In human cancer samples, IDO1 is expressed in the tumor cells, as well as in stromal cells such as monocytes/macrophages, dendritic cells (DCs), endothelial cells or fibroblasts in response to the tumor." (PMID 26895379, 2016). "Interestingly, normal breast epithelial cells in the immediate tumour proximity also showed elevated TDO2 and KMO expression, implying that IDO1/TDO2 expressing tumours have the capability to influence KP activity in surrounding normal tissue." (PMID 26646699, 2016). "Such a discrete tumoral IDO1 expression pattern was dominant in hepatocelluar carcinomas, with abundant immune cells infiltration in the same area, suggesting that IDO1 expression in these tumors are likely regulated by tumor milieus." (PMID 26895379, 2016). "Previous studies have reported the contribution of T cells in inducing IDO1 in tumor cells." (PMID 26895379, 2016). "Indeed, this IDO1-centered concept is supported by numerous preclinical studies in models of tumor immunity." (PMID 27174915, 2016). "Since the demonstration that IDO1 has immuno-suppressive ability by mediating maternofetal tolerance, much attention has been dedicated to determining how IDO1 also modulates the immune response to tumours." (PMID 26646699, 2016). "Enhanced tumor growth was blocked by treatment of mice with an IDO1 inhibitor, 5-Br-Brassinin." (PMID 27148255, 2016). "Patients who might benefit from this approach are currently identified based on expression analyses of IDO-1/-2 or TDO2 in tumor tissue and/or enzymatic activity assessed by kynurenine/tryptophan ratios in the serum." (PMID 25881064, 2015). "Our assays suggest an additional benefit of inhibiting the STAT3/IDO1 axis in resistant cells, i.e. the restoration of a significant expansion of T-lymphocytes that would be otherwise suppressed in the presence of multidrug resistant tumor cells." (PMID 25955018, 2015). "In 2003, our group showed for the first time that IDO1 was expressed in human tumors, and that, in a mouse tumor model, IDO1 protected tumors against immune rejection, an effect that could be reversed by pharmacological IDO1 blockade." (PMID 25691885, 2015). "Part of the IDO1 expression by tumor cells might result from an ongoing immune response involving T lymphocytes producing IFNγ." (PMID 25691885, 2015). "In human tumor samples, IDO1 expression is commonly observed both at the RNA and protein levels." (PMID 25691885, 2015).
tumor (continued). "Several publications have reported increased proportions of IDO1-expressing DC in tumor-draining lymph nodes (TDLN) as compared to normal lymph nodes, mostly in mouse tumor models but also in human tumors, suggesting an important role of TDLNs in shaping tumoral immune tolerance." (PMID 25691885, 2015). "Exogenous administration of the IDO1 pathway catabolites kynurenine and quinolinic acid led to activation of β-catenin and proliferation of human colon cancer cells, resulting in increased tumor growth in mice." (PMID 26378585, 2015). "1-Methyl-D-tryptophan may promote anti-tumor immune escape by increasing the IDO1 level in cancer cells." (PMID 25376937, 2015). "However, silencing the Ido1 gene by siRNA resulted in reduced tumor growth in B16F10 tumor-bearing mice." (PMID 25346733, 2014). "Moreover, a significant inverse correlation between the density of IDO1-positive microvessels and the number of proliferating tumor cells in primary and metastatic renal cell carcinoma was found." (PMID 24495478, 2014). "Thus, the evidence for IDO1 modulating host–tumor cell interactions is strong and diverse, but involvement of TDO and IDO2 is much less studied and requires further corroboration." (PMID 25346733, 2014). "However, another study in patients with HCC showed that IDO1 expression in tumor specimens was positively correlated with progression-free survival." (PMID 24495478, 2014). "Next we examined the relevance of STAT3 signaling for IDO1 expression in human tumor tissue." (PMID 24657910, 2014). "IDO1 activity in tumour cells may reflect either constitutive IDO1 protein expression or IDO1 induction as a consequence of microenvironmental interactions." (PMID 23973990, 2013). "In this specific area, IDO1 can interact with tumour-infiltrating lymphocytes." (PMID 22108515, 2012). "But, as our observations identify IDO expression as a prognostic marker, it is tempting to speculate about the role of IDO1 in tumour immune escape." (PMID 22108515, 2012). "In contrast, 4T1/Ido1− cells, in which the Ido1 gene was down-regulated via shRNA transfection, have dramatically increased sensitivity to apoptosis, thus suggesting an important antiapoptotic function of Ido1 in tumor cells." (PMID 22654951, 2012). "But, whether IDO1 activity is able to affect the amount of local tumour-infiltrating lymphocytes, which is an independent prognostic factor in patients with CRC, remains controversial." (PMID 22108515, 2012). "A tumor-related immune escape mechanism based on tryptophan degradation by IDO1 has been proposed." (PMID 22654951, 2012). "In addition, the complex interaction between IDO1 and T lymphocytes in the tumour microenvironment makes it very difficult to detect the effect of IDO1 on T lymphocytes as merely a decrease in number." (PMID 22108515, 2012). "Tumor growth from Ido1− cells was inhibited in comparison with Ido1+ cells in BALB/c mice." (PMID 22654951, 2012). "Moreover, the interplay in the tumour microenvironment becomes even more complicated if not only neoplastic epithelium, but also cells in the tumour stroma are taking into account as a possible source of IDO1 production." (PMID 22108515, 2012). "The elevated survival of mice bearing 4T1/Ido1− tumors may be a result of a less efficient immune response against tumor cells demonstrating inhibited Ido1 expression." (PMID 22654951, 2012). "Growth inhibition of Ido1− tumor cells can be attributed to a more efficient immune response." (PMID 22654951, 2012). "Cell types that express IDO1 include myeloid-lineage cells (dendritic cells, monocytes, macrophages and eosinophils), epithelial cells, fibroblasts, vascular smooth muscle cells, endothelial cells and certain tumor cell lines." (PMID 21989355, 2011).
tumor (continued). "In conclusion, we have identified the upregulation of IDO1 expression in human cancer cells as a profound effect of 1-D-MT, a compound currently used in clinical studies in patients with relapsed or refractory solid tumors with the aim of inhibiting (IDO)-mediated tumor immune escape." (PMID 21625531, 2011). "Spatial proteomic analysis revealed that EBV+DLBCL harbours a profoundly immunosuppressive tumour microenvironment characterised by relative loss of intratumoural CD8+ T cells, expansion of PD-1+ regulatory and exhausted T-cell populations and dense aggregates of PD-L1+/IDO1+ macrophages." (PMID 42271039, 2026). "The initial excitement surrounding IDO1 inhibition was supported by robust preclinical data demonstrating that pharmacological intervention could effectively reverse tumor-induced immune tolerance and potentiate the effects of other immunotherapeutic modalities." (PMID 40894232, 2025). "However, in chronic inflammatory and tumour microenvironments, the sustained high expression of IDO1 may lead to immunosuppression, making it difficult to completely eliminate pathogens or tumour cells." (PMID 40916319, 2025). "However, the function of Ido1 in non-tumor diseases remains largely unexplored." (PMID 41208887, 2025). "There are several key factors contributing to the failure of IDO1 inhibition trials, including the failure to select the appropriate patient population; it is crucial to first determine whether the tumor relies on the KYN pathway as its primary metabolic dependency before selecting it for the study." (PMID 39997327, 2025). "Moreover, the co-expression of IDO-1 and PD-L1 might be related to the enhanced anti-tumor efficacy in NSCLC clinical trials with dual blocking of PD-1/PD-L1 and IDO-1154." (PMID 40861801, 2025). "Thus, IDO1 acts as a signaling molecule in the tumor cells in response to the catalytic inhibitors." (PMID 41262240, 2025). "Besides, ER signaling might activate IDO1, creating an “ER-IDO1 immune suppression axis” that strengthens tumor resistance to immunotherapy." (PMID 40772270, 2025). "In addition, lacidipine (0.5 and 1 mg kg−1) reduced the expression of IDO1/2 in tumor tissues." (PMID 39585774, 2025). "The absence of association with IDO1 or TDO2 may indicate alternative activators within the tumour microenvironment." (PMID 40471422, 2025). "Despite this last limitation in our results, we could hypothesize the possible prognostic role of IDO-1 expression in tumor and immune cells, highlighting the relevance of IDO-1 detection in tumor tissue and the importance of further investigations in this setting." (PMID 40475772, 2025). "Notably, IDO2 exhibited a strong association with AhR expression and tumour cell density, with no observed correlation between AhR and either IDO1 or TDO2." (PMID 40471422, 2025). "Furthermore, dual metabolic modulation-such as pairing IDO1 degraders with adenosine pathway inhibitors or glutaminase blockers-may address tumor plasticity." (PMID 40894232, 2025). "Additionally, the upregulation of IDO1 may also suppress T-cell activity, promote tumor immune tolerance, and further exacerbate tumor progression." (PMID 41003841, 2025). "Additionally, tumours with a high expression of FTH1 and IDO1 may be particularly susceptible to combination strategies involving ferroptosis inducers and immune checkpoint inhibitors, offering a potential avenue for targeted therapy." (PMID 41153383, 2025). "Therefore, concurrently inhibiting both IDO1 expression and activity may yield a more effective anti‐tumor response than using IDO enzyme activity inhibitors alone, supported by our findings that lacidipine significantly enhanced T cell proliferation." (PMID 39585774, 2025). "Additionally, the kynurenine/tryptophan (Kyn/Trp) ratio in serum or tumor tissue may serve as a dynamic pharmacodynamic marker, reflecting IDO1 activity and predicting therapeutic response." (PMID 40894232, 2025).
tumor (continued). "Combination therapy produced intermediate tumor proliferation and CD8+ T cell infiltration, suggesting partial but incomplete reversal of TSC1 deficiency–induced immune evasion, likely constrained by additional immunosuppressive pathways such as IDO1 induction or Treg recruitment." (PMID 41445741, 2025). "In addition, IDO1 expression was correlated with increased tumor-infiltrating lymphocytes." (PMID 40332338, 2025). "Additionally, correlations between CD68 expression and six TIICs (B cells, CD4+ T cells, CD8+ T cells, macrophages, NK cells, and cancer-associated fibroblasts) or four common TICs (PDCD1, CTLA4, IDO1, and CD40) were assessed using the Tumor Immune Estimation Resource (TIMER)." (PMID 40918116, 2025). "Targeting IDO1 in combination with metabolic inhibitors offers a promising therapeutic avenue, as IDO1 blockade (using Epacadostat, Navoximod, Indoximod, etc.)may restore anti-tumor immunity while disrupting metabolic adaptation." (PMID 40917745, 2025). "However, in chronic inflammation and tumour microenvironments, the persistent high expression of IDO1 may result in immunosuppression, promoting the chronicity of inflammation." (PMID 40916319, 2025). "Moreover, stabilization of IDO1 enhances immunosuppressive tumor environment." (PMID 40137109, 2025). "Furthermore, constitutive expression of IDO1 prevents tumor cells from being rejected by T cells." (PMID 38813870, 2024). "However, tumor immunotherapy based solely on IDO1 inhibition may produce limited therapeutic effects in practice due to the scarce infiltration of CD8+ T cells in tumors." (PMID 38966855, 2024). "Additionally, newly published papers revealed that IDO1 also could facilitate tumor neovascularization by disturbing local innate immunity." (PMID 38227591, 2024). "Interestingly, we observed elevated expression levels of IDO1 in tumor cells." (PMID 38951801, 2024). "Interestingly, BTLA, CD200, IDO1, LAG3, TNFSF14, etc., were overexpressed in the low-risk group, suggesting that low-risk patients may get better treatment outcomes in tumor immunotherapy." (PMID 38169540, 2024). "Furthermore, we used Spearman’s correlation analysis to examine the associations between IDO1 and microsatellite instability (MSI), DNA methyltransferases (DNMTs), tumor mutational burden (TMB), the associated genes of mismatch repair (MMR), and immune checkpoint biomarkers." (PMID 38539263, 2024). "IDO1 inhibitor could reverse the tumor‐promoting effects of MSCs in vitro and in vivo." (PMID 39304650, 2024). "Moreover, selective IDO1 inhibition can itself increase TDO2 expression in tumour cells." (PMID 39048947, 2024). "Thus, inhibition of IDO1 may help restore an effective antitumor response and may also augment checkpoint inhibitor activity by reducing resistance to anti-tumor inflammatory responses." (PMID 39054462, 2024). "Therefore, the transformation of Trp through the KP, driven by the overexpression of IDO-1 in tumor cells, as well as neighboring cells (i.e., fibroblasts and infiltrating immune cells), likely constitutes a significant component of the mechanisms responsible for immune evasion." (PMID 39062529, 2024). "Therefore, the selection of IDO1 inhibitors that contribute to activating T and NK cells to break the immune tolerance of tumors may bring breakthroughs in tumor immunotherapy." (PMID 38882349, 2024). "Together, this supports the hypothesis that increased IFNγ production, from non-cell autonomous sources, is driving elevated IDO1 expression in tumour epithelial cells in Dock2 deficient mice." (PMID 39242821, 2024). "Further, we identified that aberrantly high expression levels of IDO1 related to tryptophan metabolic abnormalities in tumor cells could release L-kyn enriched EVs, contributing to increased NAD + levels of endothelial cells, which might be involved in mitophagy activation." (PMID 38468343, 2024).
tumor (continued). "Moreover, the IDO1 inhibitor could suppress endothelial mitophagy, tumor angiogenesis and progression in orthotopic OC mice." (PMID 38468343, 2024). "Notably, both endothelial mitophagy and tumor angiogenesis could be suppressed by the IDO1 inhibitor in the orthotopic OC mouse model." (PMID 38468343, 2024). "Tryptophan-2,3-dioxygenase (TDO2) and indoleamine-2,3-dioxygenase (IDO1) are structurally distinct heme enzymes that catalyze the conversion of L-tryptophan to N-formyl-kynurenine, and play important roles in metabolism, inflammation, and tumor immune surveillance." (PMID 39537789, 2024). "Furthermore, we demonstrated that the anti-tumor efficacy was markedly enhanced by co-administration of DSP-0509 with either an IDO1 inhibitor or an AXL inhibitor, although involvement of diverse immune cell except for Tregs and macrophages needs to be examined in the future study." (PMID 39346737, 2024). "Additionally, because blocking the IDO1 pathway enhanced the cytotoxic effects of Sfn in vitro, we speculated whether it could also enhance tumor immunogenicity to induce an adaptive immune response." (PMID 38884220, 2024). "IDO1 is the first rate-limiting enzyme in tryptophan catabolism, which can induce apoptosis or dysfunction of T cells and NK cells by mediating the depletion of tryptophan and the accumulation of its metabolite kynurenine, thus weakening the body's anti-tumor immunity." (PMID 38882349, 2024). "However, we observed a trend (p = ns) for increased IDO1 expression with increasing tumor grade." (PMID 38736462, 2024). "Notably, the IDO1 inhibitor could suppress endothelial mitophagy and tumor progression in the OC orthotopic mouse model." (PMID 38468343, 2024). "However, rather than a focus on neovascularization, this study focused on how IL6 and NOTCH signaling cooperate to promote cancer cell stemness, suggesting yet another possible intersectional mechanism by which IDO1 contributes to fostering a tumor-promoting inflammatory TME." (PMID 37182174, 2023). "Furthermore, the relationship between IDO1 expression and tumor characteristics in patients with EC (n = 61) was analyzed by Mann-Whitney U. The data demonstrated that expression of IDO1 was positively correlated with lymph node metastasis (N-value; P = 0.010)." (PMID 37903782, 2023). "The relevance of our discussion here is that within the milieu where tumor cells themselves acquire IDO1 expression, myeloid IDO1+ cells may also be present in large numbers, and we now know that IL4i1 can also contribute to tryptophan metabolic flux in the same environment." (PMID 37196768, 2023). "Surprisingly, although Ido1, Ido2 and Tdo2 were barely expressed in MEPs, a high level of Kyn was found in the MEPs of tumor-bearing mice and a very low Kyn level was present in the MEPs of tumor-free mice, suggesting that MEPs from tumor-bearing hosts might use exogenous Kyn to activate AhR." (PMID 37919525, 2023). "The blockage of IDO1 may be used clinically to inhibit tumor evasion from immune surveillance." (PMID 38037752, 2023). "Therefore, IDO1 inhibitors not only exert anti-tumor activity but also may enhance the therapeutic effect of PD-1/PD-L1 inhibitors when combined with PD-1/PD-L1 inhibitors." (PMID 37334368, 2023). "In addition, IDO1 expression in the tumor can induce expression of PD-1 in T cells." (PMID 37040510, 2023). "In addition, IDO-1 activity leads to the suppression of effector T and NK cells and the promotion of angiogenesis in solid tumors, while IDO-1 deficiency causes a stark depletion of Tregs and tumor rejection mediated by CD4+ and CD8+ T cells." (PMID 37046685, 2023).